TREM2 (triggering receptor expressed on myeloid cells 2)
Diseases named in the same sentence as TREM2 in open-access papers (continued):
Sharing a sentence is not in itself a finding about the gene and the disease.
keratitis (2 papers, 2018 to 2025). A corneal disease that is characterized by inflammation of the cornea. "In this study, we investigated the function and regulatory mechanism of TREM2 in Pseudomonas aeruginosa (P. aeruginosa) keratitis." (PMID 29887864, 2018). "We found that P. aeruginosa keratitis was more severe in Trem2−/− versus wild type C57BL/6 mice as indicated by the increased clinical scores, bacterial load, and cornea pathology." (PMID 29887864, 2018). "Our study demonstrated that TREM2 promotes host resistance against P. aeruginosa keratitis by inhibiting caspase-1-dependent pyroptosis, which provides new insights of TREM2-mediated anti-bacterial immunity." (PMID 29887864, 2018).
kidney cancer (2 papers, 2021 to 2022). Primary or metastatic malignant neoplasm involving the kidney. "For instance, HLRCC-associated kidney cancer harbors suppressed T cells and TREM2-high macrophages, which may lead to immune tolerance." (PMID 35874919, 2022).
leprosy (2 papers, 2022 to 2025). Leprosy is a chronic infectious disease affecting primarily the skin and peripheral nervous system. "While TREM2+ macrophages were associated with immunological failure in leprosy, most TREM2+ macrophages were from wounded sites in our study." (PMID 39882906, 2025). "IL-10 is a cytokine associated with the induction of a phagocytic and permissive macrophage phenotype in leprosy patients and we can suggest that the regulation of TREM2 after MDT in MB patients may impact the outcome of the treatment." (PMID 35937686, 2022).
lipid metabolism disorder (2 papers, 2023 to 2025). "This narrative review is based on the core pathogenesis of lipid metabolism disorder and immune response imbalance in MASH, taking TREM2 as the entry point." (PMID 40636122, 2025).
lung squamous cell carcinoma (2 papers, 2021 to 2022). "However, in other cancers, such as lung squamous cell carcinoma, TREM2 staining was moderate in the normal tissue and weak in the tumor tissue." (PMID 36119485, 2022).
malaria (2 papers, 2017 to 2021). Malaria is a serious and sometimes fatal disease caused by a parasite that commonly infects a certain type of mosquito which feeds on humans. "We have previously shown that expression of innate immunity receptors in Kupffer cells, namely, TREM2, is involved in the genetic resistance to malaria liver stage infection in mouse models." (PMID 28220125, 2017). "A study has demonstrated that Trem-2-deficient mice infected with P. berghei ANKA (PbANKA) sporozoites are more susceptible to liver-stage infection than their wild-type counterparts, and TREM-2 is involved in host responses against the malaria parasite." (PMID 34899708, 2021).
muscular dystrophy (2 papers, 2024). Muscular dystrophy (MD) refers to a group of more than 30 genetic diseases characterized by progressive weakness and degeneration of the skeletal muscles that control movement. "The SPP1 gene, implicated in muscular dystrophy and bone loss, exhibits high expression in TREM2+ lipid-associated macrophages, suggesting its conserved role in age-related characteristics." (PMID 38248779, 2024). "Regarding the functions of TREM2+ Macs in aged individuals, we found that SPP1, which promotes fibrosis in muscular dystrophy and bone destruction, was highly expressed in TREM2+ Macs." (PMID 38088531, 2024).
ovarian tumor (2 papers, 2024). "Further investigation into TREM2 as a potential clinical target has culminated in a clinical trial testing the efficacy of a humanized TREM2 targeting antibody in unresectable or metastatic breast, colorectal, lung, renal, and ovarian tumors after relapse following standard of care treatment." (PMID 38426622, 2024). "In addition, ovarian tumor is TREM2 rich; therefore, it may benefit from anti-TREM2 mAb treatments." (PMID 39003350, 2024).
peripheral nerve injury (2 papers, 2018 to 2020). Injury to a peripheral nerve. "Intriguingly, while TREM2/DAP12-mediated microglial activation is detrimental for some diseases, including peripheral nerve injury, it is beneficial for other diseases." (PMID 30127720, 2018).
pneumococcal infection (2 papers, 2014 to 2024). Infections with bacteria of the species streptococcus pneumoniae. "In this report we examine the function of TREM-2 in the context of Streptococcus pneumoniae infection, the most frequent cause of community acquired pneumonia." (PMID 24945405, 2014). "For instance, TREM2-deficient alveolar macrophages (AMs) produce less TNF-α and cytokine-induced neutrophil chemoattractant after Streptococcus pneumoniae infection." (PMID 39405126, 2024). "Here, we established the presence of TREM-2 on alveolar macrophages (AM) and explored the function of TREM-2 in the innate immune response to pneumococcal infection in vivo." (PMID 24945405, 2014).
primary progressive aphasia (2 papers, 2016 to 2024). Primary progressive aphasia (PPA) is a neurodegenerative disorder, characterized by a primary dissolution of language, with relative sparing of other mental faculties for at least the first 2 years of illness. "TREM2 variants have been reported in a diverse array of neurodegenerative disorders, including NHD, FTD, AD, PD, semantic variant of primary progressive aphasia (svPPA), and ALS." (PMID 38888203, 2024).
pulmonary sarcoidosis (2 papers, 2015 to 2020). Sarcoidosis affecting the lung parenchyma. "Our results show differences in TREM-1 and TREM-2 expression on CD14+ cells in bronchoalveolar lavage between pulmonary sarcoidosis and HP." (PMID 32508528, 2020). "In contrast to TREM-1, we identified significant differences in TREM-2 expressions on myeloid cell surfaces in BALF of pulmonary sarcoidosis patients." (PMID 26166951, 2015).
sleep disorder (2 papers, 2024 to 2025). A change from the patient's baseline sleeping pattern, in the hours slept and/or an alteration/dysfunction in the stages of sleep. "Soluble TREM2, the extracellular segment of TREM2 (sTREM2) released after proteolytic cleavage, showed higher levels in the cerebrospinal fluid (CSF) of PD patients compared to healthy controls, especially in patients with sleep disorders, with a positive correlation with α-syn levels." (PMID 40309835, 2025).
viral hepatitis (2 papers, 2017 to 2022). An acute or chronic inflammation of the liver parenchyma caused by viruses. "In this study, we report a novel pathogenic role for TREM2 that results in aggravated viral hepatitis." (PMID 28900132, 2017). "Collectively, these experiments show that loss of TREM2 in the non-hematopoietic compartment results in ameliorated viral hepatitis." (PMID 28900132, 2017). "TREM2 was not detectable in primary hepatocytes and we, thus, hypothesize that a non-hematopoietic cell population other than hepatocytes is exerting the detrimental effects of TREM2 observed in our model of viral hepatitis." (PMID 28900132, 2017). "Our study revealed global changes in circulating lipids in the sera of LCMV-infected mice and identified a novel detrimental role for the non-hematopoietically expressed lipid-sensor TREM2 in a model of viral hepatitis." (PMID 28900132, 2017). "Thus, the fact that both Trem2−/− and Trem1−/− mice show a protective phenotype in viral hepatitis indicates distinct cell type-specific and non-redundant roles of these TREM family members in liver pathology." (PMID 28900132, 2017).
Adult onset (1 paper, 2022). Onset of disease manifestations in adulthood, defined here as at the age of 16 years or later. "There are obvious parallels with another adult-onset microgliopathy, Nasu–Hakola disease, which is associated with mutations in TREM2 or the adaptor, TYROBP, which lie downstream of CSF1R in regulation of microglial survival." (PMID 35333324, 2022).
aneurysm (1 paper, 2025). Bulging or ballooning in an area of an artery secondary to arterial wall weakening. "Recently, bone‐marrow transplantation also demonstrated that TREM2+ macrophages were key mediator of vascular damage and aneurysm development, in agreement with our findings." (PMID 41058009, 2025).
ankylosing spondylitis (1 paper, 2025). An autoimmune chronic inflammatory disorder characterized by inflammation in the vertebral joints of the spine and sacroiliac joints. "This study identifies TREM2+ macrophages as key contributors to pathological bone formation in ankylosing spondylitis (AS)." (PMID 40091508, 2025).
Apathy (1 paper, 2025). Apathy is a quantitative reduction of interest, motivation and the initiation and persistence of goal-directed behavior, where often the accompanying emotions, thoughts, and social interactions are also diminished. "Composite apathy scores were strongly and positively correlated with mRNA fold changes for all examined genes: Tyrobp, Trem2, C1qa, C1qb, C1qc, C3, C3ar1, and Cd33 (p < 0.0001)." (PMID 41377997, 2025). "Tyrobp (r = 0.8088) and Trem2 (r = 0.8034), which are upstream regulators of complement signaling, exhibited strong correlations with apathy scores." (PMID 41377997, 2025).
Aphasia (1 paper, 2019). An acquired language impairment of some or all of the abilities to produce or comprehend speech and to read or write. "On the other hand, potential risk mutations were found in patient #2, such as P513A in MAPT, which was suggested to play a role in progressive non-fluent aphasia, or TREM2 p.P211L, which may be a risk modifier for AD/FTD." (PMID 30917570, 2019).
Ascites (1 paper, 2026). Accumulation of fluid in the peritoneal cavity (between the layers of the peritoneum that lines the abdomen). "Although TREM2+ macrophages are enriched in malignant ascites, the role of soluble TREM2 (sTREM2) in regulating vascular function and ascites pathogenesis remains poorly understood." (PMID 42192204, 2026).
astrocytoma (1 paper, 2017). "Unidentified TREM2 ligands were also detected by TREM2-Fc binding to the cell surface of macrophages, human astrocytoma cells, dendritic cells, N2A cells, THP-1 cells and apoptotic cells." (PMID 28768545, 2017).
atrial fibrillation (1 paper, 2025). A disorder characterized by an electrocardiographic finding of a supraventricular arrhythmia characterized by the replacement of consistent P waves by rapid oscillations or fibrillatory waves that vary in size, shape and timing and are accompanied by an irregular ventricular response. "These TREM2+ macrophages may express SPP1 and are involved in liver and lung fibrosis, as well as fibrosis after myocardial infarction and atrial fibrillation." (PMID 40072075, 2025).
autoimmune encephalitis (1 paper, 2020). Inflammation of the brain secondary to an immune response triggered by the body itself. "In experimental autoimmune encephalitis, the expression levels of TREM2 on the surface of microglia increased significantly under inflammation." (PMID 32117023, 2020).
bladder cancer (1 paper, 2024). "In bladder cancer (BLCA), TREM2 expression is also associated with tumor progression and decreased immunotherapy efficacy, and TREM2 may play a role by promoting epithelial mesenchymal transition (EMT) and T-cell exhaustion." (PMID 38725629, 2024).
brain glioma (1 paper, 2025). A malignant glioma that involves the brain. "However, other studies have shown that TREM2 exhibits distinct immune regulatory roles in brain gliomas and peripheral tumors, and it primarily exerts a protective function in brain gliomas." (PMID 40242752, 2025).
Cerebral atrophy (1 paper, 2025). Atrophy (wasting, decrease in size of cells or tissue) affecting the cerebrum. "Aging mice with TREM2 haploinsufficiency further exhibit diminished microglial responsiveness to tissue injury and more severe cerebral atrophy." (PMID 41168805, 2025).
cerebral lesions (1 paper, 2024). "TREM2 has been shown to play roles in macrophage activation in response to cerebral lesions and pathological stimuli." (PMID 38392305, 2024).
cognition (1 paper, 2022). Intellectual or mental process whereby an organism becomes aware of or obtains knowledge. "Even though its protective and harmful roles during the pathogenesis of AD remain incompletely defined, increasing evidence suggest that TREM2 is closely related to microgliosis, astrogliosis, neuroinflammation, neuronal loss and cognition impairment in AD." (PMID 36185485, 2022).
coronary atherosclerosis (1 paper, 2022). Atherosclerosis of the coronary vasculature. "This is the first study to show that circulating soluble TREM2 levels can independently predict long-term cardiovascular outcomes in patients with coronary atherosclerosis." (PMID 36361908, 2022). "If this finding is further corroborated by larger studies, soluble TREM2 may stand as a novel biomarker of prognosis in patients with coronary atherosclerosis and pave the way to an improved understanding of the mechanisms governing plaque destabilization." (PMID 36361908, 2022). "No study has yet tested the levels of circulating soluble TREM2 in patients with coronary atherosclerosis." (PMID 36361908, 2022).
Creutzfeldt-Jakob disease (1 paper, 2017). "The TREM2 R47H variant has also been investigated as a risk factor for posterior cortical atrophy, multiple system atrophy, essential tremor, multiple sclerosis and Creutzfeldt-Jakob disease (CJD), though these studies were not conclusive." (PMID 28768545, 2017).
diabetic foot ulcers (1 paper, 2025). "In diabetic foot ulcers (DFU), the expression of TREM2 may influence the proliferation and migration abilities of keratinocytes." (PMID 41465092, 2025).
diarrhoea (1 paper, 2022). "Other DEGs that were down-regulated in the high-diarrhoea group include Ovar-DRB1, DQA, TREM2, TFF3, ITLN2, CD74, CCL5, and CCR3." (PMID 35140270, 2022).
disc degeneration (1 paper, 2024). "While H2O2 elevated TREM2 expression, causing disc degeneration, RSL downregulated TREM2 expression." (PMID 39194540, 2024). "Additionally, RSL downregulated TREM2 expression, which is elevated by H2O2 and causes disc degeneration." (PMID 39194540, 2024). "Thus, our findings imply that RSL supports human NP cells under oxidative stress and regulates the pathways underlying disc degeneration, particularly TREM2, and that RSL extracts may potentially prevent IDD." (PMID 39194540, 2024).
endometriosis (1 paper, 2023). The growth of functional endometrial tissue in anatomic sites outside the uterine body. "Trem2+ uterine macrophages contribute to the migration of endometriotic epithelial cells in endometriosis." (PMID 37901247, 2023).
essential tremor (1 paper, 2015). A relatively common disorder characterized by a fairly specific pattern of tremors which are most prominent in the upper extremities and neck, inducing titubations of the head. "The p.R47H mutant (associated with genetic risk of AD, PD, ALS, and essential tremor) showed slightly less, albeit similar patterns of cell-surface TREM2 expression, maturation, and sTREM2 generation compared with non-mutated TREM2." (PMID 26337043, 2015). "TREM2 is a premier example of how mutations in a microglial receptor can lead to aberrant innate immune cell signaling that contributes to the initiation and propagation of neurodegenerative phenotypes including NHD/PLOSL, FTD, AD, PD, ALS, and essential tremor." (PMID 26337043, 2015).
geographic atrophy (1 paper, 2025). "That study identified a specific subset of TREM2+ and galectin‐3 (GAL3+) microglia enriched in the macular region of patients with AMD, particularly in the subretinal space and in areas of geographic atrophy." (PMID 40716081, 2025).
herpes simplex (1 paper, 2023). "Here, we report that herpes simplex virus type 1 (HSV1) infection of human induced pluripotent stem cell (hiPSC)–derived microglia down-regulates expression of genes in the TREM2 pathway." (PMID 37595041, 2023).
Immunodeficiency (1 paper, 2023). Failure of the immune system to protect the body adequately from infection, due to the absence or insufficiency of some component process or substance. "Despite NSG mouse immunodeficiency, four of the PDX models partially reconstructed the vascular and immune-microenvironment observed in patients, among which the macrophagic TREM2/TYROBP axis expression, recently linked to immunosuppression." (PMID 37377921, 2023). "Strikingly, the best contributor genes to MPC2 involved TREM2/TYROBP, an axis associated with immunosuppression, suggesting that MPC2 might correspond to tumor associated macrophage (TAM) infiltrates despite the immunodeficiency of NSG mice." (PMID 37377921, 2023).
lentivirus infection (1 paper, 2024). Virus diseases caused by the Lentivirus genus. "After 72 h of infection, the effect of lentivirus infection was observed by fluorescence microscope, and the interference efficiency of TREM2 was detected by fluorescence quantitative PCR and Western blot." (PMID 37917301, 2024).
leukemia (1 paper, 2025). A malignant (clonal) hematologic disorder, involving hematopoietic stem cells and characterized by the presence of primitive or atypical myeloid or lymphoid cells in the bone marrow and the blood. "Consistently, we observed multiple peaks in the upstream region of TREM2 in a ZEB2 ChIP-seq profile of K562 leukemia-derived cells." (PMID 41300781, 2025).
Lipid storage disease (1 paper, 2020). "In support of a strong link between TREM2 and lipid metabolism are also the original reports describing NHD as a lipid storage disease due to a genetic enzymatic defect leading to lipid and cholesterol accumulation in the brain and bone cysts." (PMID 32772264, 2020).
lipodystrophy (1 paper, 2019). A congenital or acquired disorder characterized by abnormal loss or redistribution of the adipose tissue in the body. "We speculate that in mice of HFD feeding, adipogenesis is suppressed due to loss of TREM2, which leads to lipodystrophy." (PMID 31477129, 2019).
localized scleroderma (1 paper, 2024). Localized scleroderma is the skin localized form of scleroderma characterized by fibrosis of the skin causing cutaneous plaques or strips. "Here, immunofluorescence was performed to examine TREM2+ MФs alteration in human skin lesions of diffuse cutaneous SSc (dcSSC) and localized scleroderma (LS), and found that there was a dramatic upregulation of CD68+TREM2+ MФs during skin fibrosis progression." (PMID 38505612, 2024).
lupus (1 paper, 2025). "Furthermore, TREM2 deficiency in DCs alleviates kidney damage and reduces serum anti-dsDNA antibody levels, proteinuria, splenomegaly, and lymphadenopathy in lupus mice." (PMID 41276972, 2025). "Inhibition of NETs formation or MPO effectively alleviates TREM2-mediated lupus progression." (PMID 41276972, 2025).
lymphopenia (1 paper, 2022). Reduction in the number of lymphocytes. "However, these patients too are unable to mount an adaptive immune response due to lymphopenia or diminished T-cell priming as a result of depleted TREM2+ DCs." (PMID 35438176, 2022).
metastatic melanoma (1 paper, 2023). A melanoma that has spread from its primary site to another anatomic site. "Moreover, we used the gene signature of TREM2+ TAMs to perform GSEA on RNA-seq data of 29 patients with metastatic melanoma who had been treated with anti-PD1." (PMID 37187751, 2023).
Motor axonal neuropathy (1 paper, 2024). Progressive impairment of function of motor axons with muscle weakness, atrophy, and cramps. "Moreover, TREM2 deficiency impairs energy metabolism and axonal growth in sciatic nerve, accompanied by exacerbation of neurological deficits and suppression of nerve regeneration in a mouse model of acute motor axonal neuropathy." (PMID 38453910, 2024). "Moreover, TREM2 deficiency disrupts the energy metabolism of the sciatic nerve and impairs support for axonal regeneration, accompanied by exacerbation of neurological deficits and suppression of nerve regeneration in a mouse model of acute motor axonal neuropathy (by FigDraw)." (PMID 38453910, 2024).